SLC3A2 (solute carrier family 3 member 2)
Diseases named in the same sentence as SLC3A2 in open-access papers (continued):
Sharing a sentence is not in itself a finding about the gene and the disease.
breast cancer (continued). "Due to the significant association of the SLC7A5+SLC3A2+ subgroup of patients with a high rate of mitotic activity (p < 0.0001), we next investigated if SLC7A5/SLC3A2 co-expression is associated with proliferation of ER+ breast cancer." (PMID 32093034, 2020). "To further investigate whether SLC7A5/SLC3A2 co-expression affects the response of ER+ breast cancer cells to tamoxifen, we knocked down SLC7A5 and SLC3A2 in combinations in MCF7 and MDA-MB-175-VII cells using siRNAs." (PMID 32093034, 2020). "Here we showed that high co-expression of the SLC7A5/SLC3A2 complex could be used as a prognostic marker to predict a poor response to endocrine treatment in ER+ breast cancer." (PMID 32093034, 2020). "This was consistent when analysing protein expression, where SLC7A5+SLC3A2+ co-expression was shown to predict a high risk of distant metastasis and death from breast cancer (p < 0.05), but not recurrence (p = 0.25)." (PMID 32093034, 2020). "On the basis of our findings, SLC7A5/SLC3A2 co-expression has the potential of identifying a subgroup of ER+/HER2− breast cancer patients who fail to benefit from endocrine therapy and could guide the choice of other alternative therapies." (PMID 32093034, 2020). "Thus, the co-expression of ASCT2, SLC7A5 and SLC3A2 may serve as potential biomarkers for identifying ER+ highly proliferative subclass and HER2+ subclass of breast cancer patients at higher risk of poor response to endocrine therapy." (PMID 41154605, 2025). "Additionally, SLC3A2 was a target gene of ZEB1 in breast cancer chemoresistance, it maybe the chemotherapy of laryngeal carcinoma is associsated with the result of high SLC3A2 patients with longer survival." (PMID 35057861, 2022). "These analyses confirmed aberrantly high expression of LAT1 (SLC7A5) and its heterodimeric heavy chain, SLC3A2, in cell lines and clinical samples, with significantly higher expression in more proliferative breast cancer subtypes (basal, claudin-low, HER2; p < 0.0001, Kruskal-Wallis test)." (PMID 29940911, 2018). "Together, these results indicate that ERα is recruited to the ERE-containing promoters in SLC7A11 and SLC3A2, thereby enhancing SLC7A11 and SLC3A2 expression in response to estrogen stimulation in ER+ breast cancer cells." (PMID 39833180, 2025). "Since ERα transcriptionally upregulated SLC7A11 and SLC3A2 expression, we believe that estrogen/ERα inhibits ferroptosis mainly through the xc−-GPX4 axis in ER+ breast cancer." (PMID 39833180, 2025). "Our research revealed that estrogen/ERα signaling inhibits ferroptosis in ER+ breast cancer by upregulating the expression of SLC7A11 and SLC3A2." (PMID 39833180, 2025). "Our research revealed that estrogen suppresses ferroptosis in ER+ breast cancer by increasing the expression of SLC7A11 and SLC3A2." (PMID 39833180, 2025). "During the processes of everolimus-inducing ferroptosis in breast cancer cells, an everolimus-related protein named FK506-binding protein 1A (FKBP1A) negatively regulates the SLC3A2 expression to promote anti-proliferation effect of Th9 lymphocytes." (PMID 38705513, 2024). "SLC7A11 (xCT), SLC3A2 (xCT), and GPX4 expression have been reported to be elevated in a subset of TNBC breast cancer models predicting response to erastin (xCT inhibitor) and RSL3 (GPX4 inhibitor)." (PMID 37596261, 2023). "The high expression of disulfidptosis genes (e.g., SLC3A2, RPN1, BRK1, ACTR2, ACTR3, SLC7A11, and NCKAP1) in the KM analysis of breast cancer indicated the poor prognosis of patients." (PMID 38035071, 2023). "Both SCRIB and SLC3A2 are required for cell proliferation and tamoxifen resistance in ER+ cells identifying a new role for the SCRIB/SLC3A2 complex in ER+ breast cancer." (PMID 35501367, 2022). "To understand the relationship between SLC3A2 and SLC7A5 in their ability to regulate the proliferation of ER+ breast cancer cells, we analyzed changes in the protein levels of each other." (PMID 35501367, 2022).
breast cancer (continued). "This revealed numerous genes whose expression was altered by reducing YB-1, including several related to hypoxia (e.g., PPIF, SLC3A2 and SLC7A1) and found to be elevated in breast cancers with increased expression or amplification of YB-1." (PMID 34294889, 2022). "Meanwhile, SLC3A2 has been reported to bind with cystine transporter xCT/SLC7A11, which has an essential function in the growth of ER- breast cancer cells." (PMID 35501367, 2022). "Upregulation of xCT subunits, solute carrier family 7 number 11 (SLCA11) or solute carrier family 3 member 2 (SLC3A2), increased the GPX4 expression, but paradoxically hypersensitized breast cancer cells to erastin or RSL3-induced ferroptosis." (PMID 36211509, 2022). "Comparative metabolite analysis identified eight metabolites, including leucine, that were downregulated in SLC3A2-KD and SCRIB-KD in ER+ breast cancer cells, suggesting that SCRIB and SLC3A2 targets leucine uptake in ER+ breast cancer cells." (PMID 35501367, 2022). "We find that GPX4 is strongly upregulated in a subset of breast cancer tissues compared to matched normal samples, and that this is tightly correlated with the increased expression of the xCT subunits SLC7A11 and SLC3A2." (PMID 33672555, 2021). "Despite several studies that have shown the prognostic role of SLC7A5 or SLC3A2 in cancers, the relation of their co-expression with endocrine therapy efficacy in ER+/HER2− breast cancer has yet to be reported." (PMID 32093034, 2020). "A, gene expression (mRNA log2 values) of LAT common heavy chain (SLC3A2) and LAT transporters (LAT3/SLC43A1, LAT4/SLC43A2), was analysed in all breast cancer cell lines (n = 55) included in The Cancer Cell Line Encyclopedia (TCCLE)." (PMID 29940911, 2018). "Importantly, malignant breast cancer tissues exhibited higher protein levels of SLC7A11 and SLC3A2 compared to benign breast tissues, indicating a positive association of SLC7A11 and SLC3A2 levels with poor prognosis in breast cancer patients." (PMID 39833180, 2025). "Endocrine resistant ER+ breast cancer has elevated levels of SLC7A11 and SLC3A2." (PMID 39833180, 2025). "Our study implicates that targeting the estrogen-dependent system xc−, specifically SLC7A11 and SLC3A2, with IKE through induction of ferroptosis in ER+ breast cancer cells, should offer a new therapeutic option for patients with ER+ breast cancer, particularly those with endocrine resistance." (PMID 39833180, 2025). "Since the combination of overexpressing SLC7A11 and SLC3A2 partially alleviated ferroptosis induced by ERα knockdown, it is also possible that estrogen/ ERα regulates ferroptosis through xc−-GPX4 independent pathway in ER+ breast cancer cells." (PMID 39833180, 2025). "The cell polarity protein SCRIB regulates the intracellular localization of SLC3A2 in ER+ breast cancer cells, without affecting its expression level." (PMID 39833180, 2025). "stated that SLC3A2 is an immuno-oncogenic factor that its expression is accompanied by infiltration of cytotoxic T cells, but not other immune cells among breast cancer TME." (PMID 38705513, 2024). "High expression of SLC3A2 mRNA correlated with poor clinical prognosis in ER+/PR+ but not ER−/PR− breast cancer patients." (PMID 35501367, 2022). "Our results thus far suggest that xCT positive breast cancer cells—Those expressing high levels of both SLC7A11 and SLC3A2—Are able to drive GPX4 expression through the selenocysteine biosynthesis pathway, and also are able to resist lipid prooxidant-induced death." (PMID 33672555, 2021). "Recent studies showed that high expression of different AA transporters, such as SLC3A2 or SLC7A5, is related to poor outcomes in the luminal B ER+ breast cancer subtype, suggesting that this subtype might be particularly vulnerable to glutamine depletion." (PMID 31152137, 2019).
breast cancer (continued). "Since overexpression of SLC7A11 and SLC3A2 also reduced sensitivity of ER+ breast cancer cells to Fulvestrant treatment, we hypothesized that drug targeting SLC7A11 and SLC3A2 should have efficacy against endocrine-resistant breast tumors by inducing ferroptosis." (PMID 39833180, 2025). "Also, in estrogen-receptor (ER) positive breast cancer cells, it was revealed that co-expression of SLC7A5/SLC3A2 leads to increased proliferation in cancer cells and is associated with poor prognosis, while their knocking down using siRNA-sensitized breast cancer cells to tamoxifen." (PMID 38705513, 2024). "SLC1A5, SLC3A2, SLC7A5, and SLC6A14 may be promising biomarkers for BC [breast cancer] diagnosis and may represent potential therapeutic targets for these patients”." (PMID 37627015, 2023). "SLC3A2 is broadly expressed in ER+, HER2+, and basal breast cancer cell lines without any specific expression pattern." (PMID 35501367, 2022). "Indeed, in the TBCP-1 breast cancer cell line, though neratinib did not alter GPX4 protein level, neratinib downregulated SLC3A2 expression and cysteine import." (PMID 39002022, 2024).
lung carcinoma (25 papers, 2012 to 2026). "For Lung cancer, solute carrier family 3 member 2 (SLC3A2) acts as a metabolic switch factor in tumor-associated macrophages (TAM), suggesting that lung adenocarcinoma (LUAD) phenotyping reprogramming occurs via arachidonic acid." (PMID 39484162, 2024). "Solute carrier family 3 member 2 (SLC3A2) can associate with integrin-β chains like Integrin beta 4 (ITGB4) in lung cancer, thereby influencing integrin signaling, cell survival, and cell migration." (PMID 39228892, 2024). "Studies also have shown that SLC3A2 is overexpressed in lung cancer and is associated with poor prognosis." (PMID 34638461, 2021). "Also, SLC3A2 overexpression in lung cancer was related to tumor-associated macrophages (TAMs) and poor prognosis." (PMID 38705513, 2024). "Solute carrier family 3 member 2 (SLC3A2), or CD98hc, encodes another subunit of heterodimeric amino acid transporter that is overregulated in six lung cancer datasets and establishes a heterodimeric transmembrane protein complex with SLC7A5 to catalyze amino acid transport." (PMID 39228892, 2024). "However, to our knowledge, no previous studies have shown the diagnostic or prognostic roles of serum SLC3A2 in lung cancer." (PMID 36358610, 2022). "Interestingly, we found that the SLC3A2 mRNA levels in lung cancer were associated with methylation." (PMID 36358610, 2022). "SNHG1 also functions as a transcriptional regulator to promote the transcription of its neighboring gene SLC3A2 in cis in gastric cancer, colorectal cancer, liver cancer, and lung cancers." (PMID 40510136, 2025). "Taken together, SLC3A2 is significantly overexpressed in lung cancer tissues and patient serum, highlighting its potential as a diagnostic and prognostic biomarker." (PMID 41154605, 2025). "It was found that silencing SLC3A2 in lung cancer cells inhibits M2 polarization of macrophages, changes the cancer cell's metabolism, and alters metabolites such as arachidonic acid in the TME." (PMID 38705513, 2024). "The in-depth study of SLC3A2 can provide a new molecular target for the early diagnosis, treatment, and prognosis of lung cancer." (PMID 36358610, 2022). "All this evidence indicates that SLC3A2 has important application value in the early diagnosis, histological classification, clinical stage, prognosis, and efficacy monitoring of lung cancer." (PMID 36358610, 2022). "In this study, we used the TCGA database to provide an overview of SLC3A2 expression in different subgroups of lung cancer patients." (PMID 36358610, 2022). "The protein SLC7A5 is part of a two‐protein complex with SLC3A2 and the gene was hypermethylated and its expression increased in lung cancer." (PMID 30761256, 2019). "Tissues and cell lines representing several cancers including lung cancer have high SLC3A2 expression, which contributes to cell proliferation and adhesion." (PMID 27626312, 2016). "Additionally, several amino acid transporters, namely ASCT2, LAT1 and SLC3A2, are dysregulated in lung cancer, contributing to tumour growth, survival, and metabolic reprogramming." (PMID 41154605, 2025). "In lung cancer cells, tumorigenesis was triggered by SLC3A2 through the MEK/ERK signaling pathway." (PMID 38223725, 2024). "The impact of SLC7A11 and SLC3A2 on the prognosis of lung cancer have been documented, it is still uncertain whether NCKAP1 and GYS1 influence the prognosis in lung cancer remains unclear." (PMID 38223725, 2024). "Previous studies have shown that SLC3A2 has a higher level in lung cancer." (PMID 36387251, 2022). "In summary, we identified that the four ferroptosis suppressor genes, ACSL3, CISD1, FANCD2, and SLC3A2, could increase the cancer stemness, indicating that the lower the ferroptosis level in lung cancer cells, the higher the tumor heterogeneity." (PMID 34434214, 2021). "In addition, SLC3A2 induced tumorigenesis via the MEK/ERK signaling pathway in lung cancer cells." (PMID 36358610, 2022).
lung carcinoma (continued). "The diagnostic or prognostic roles of serum SLC3A2 in lung cancer are still not clear." (PMID 36358610, 2022). "SLC3A2 heterodimerizes with SLC7A5/LAT1, which has a well-established role in lung cancer." (PMID 36996232, 2023).
glioma (16 papers, 2011 to 2025). A benign or malignant brain and spinal cord tumor that arises from glial cells (astrocytes, oligodendrocytes, ependymal cells). "In summary, in this study, we have identified SLC3A2 as a critical factor associated with poor prognosis and enhanced malignancy in gliomas." (PMID 38977800, 2024). "Nevertheless, the association of SLC3A2 with gliomas and the potential biological effects in gliomas remain to be investigated." (PMID 38977800, 2024). "Elevated SLC3A2 was revealed as an independent risk element for poor glioma prognosis through Cox regression analyses." (PMID 38977800, 2024). "Univariate Cox regression analysis has discerned significant associations between glioma patient survival trajectories and the expression profiles of several disulfidptosis-related genes, specifically SLC3A2, RPN1, NCKAP1, and SLC7A11 (all, P < 0.05)." (PMID 38977800, 2024). "In TCGA datasets of glioma, a grand total of 596 DEGs associated with SLC3A2 were detected." (PMID 38977800, 2024). "Therefore, SLC3A2 is a prognostic biomarker and associated with immune infiltration in gliomas." (PMID 38977800, 2024). "GYS1, NDUFA11, OXSM, RPN1, and SLC3A2 play a role in promoting cancer in glioma, while LRPPRC, NCKAP1, NDUFS1, NUBPL and SLC7A11 play a role in inhibiting tumour." (PMID 39993959, 2025). "Recently, the disulfidptosis related genes (DRGs) SLC3A2, NDUFA11, OXSM, NUBPL, LRPPRC, RPN1, and GYS1 were found to be significantly associated with glioma cells." (PMID 40109666, 2025). "The upregulation of the disulfidptosis-related gene SLC3A2 influences immune cell infiltration in gliomas, notably macrophage infiltration, and impacts tumor migration and invasion, consequently affecting the tumor microenvironment." (PMID 40109666, 2025). "SLC3A2 potentially functions as an oncogene, altering the tumor microenvironment, thus playing a crucial role in the pathobiology of gliomas." (PMID 38977800, 2024). "CCK8, colony formation, migration, and invasion assays were utilized in vitro, and an orthotopic glioma xenograft model was employed in vivo, to investigate the role of SLC3A2 in gliomas." (PMID 38977800, 2024). "This study delves into the expression of SLC3A2 in gliomas to assess its utility as a prognostic marker." (PMID 38977800, 2024). "To elucidate the prognostic impact of SLC3A2 on glioma, we employed the survival analysis to interrogate data from TCGA-GBMLGG and CGGA patient cohorts." (PMID 38977800, 2024). "Utilizing a robust bioinformatics approach, we analyze expression data from extensive cancer databases, striving to decipher the prognostic significance of SLC3A2 and its relationship with immune infiltration and metabolic pathways in glioma cells." (PMID 38977800, 2024). "A meta-analysis spanning the three cohorts reinforced these findings, indicating a unified HR of 1.72 (95% CI, 1.30–2.29) and negligible heterogeneity (I2 = 21.8%), thus firmly establishing high SLC3A2 expression as a harbinger of poor glioma prognosis." (PMID 38977800, 2024). "Experimental evidence also suggests that reducing SLC3A2 levels decreases tumor cell proliferation, migration, and invasion, and hampers glioma growth in vivo." (PMID 38977800, 2024). "In doing so, the research presented herein seeks to elucidate the multifaceted role of SLC3A2 in glioma pathobiology and its prognostic significance in gliomas through rigorous and accurate analyses." (PMID 38977800, 2024). "We evaluated the expression of SLC3A2 and its prognostic importance in gliomas using publicly accessible databases and our clinical glioma samples and with reliance on Meta and Cox regression analysis approaches." (PMID 38977800, 2024). "Spearman correlation analyses were employed to elucidate the interplay between SLC3A2, RPN1, NCKAP1, and SLC7A11 within the glioma landscape, revealing the strongest correlation between SLC3A2 and SLC7A11 (R = 0.242, P < 0.001)." (PMID 38977800, 2024).